CD28 (CD28 molecule)
Diseases named in the same sentence as CD28 in open-access papers (continued):
Sharing a sentence is not in itself a finding about the gene and the disease.
infection (continued). "The optimal infection time was set up after 48 hours of OKT3 activation, since at this time point we obtained the highest percentage of CAR-expressing T cells, and a less differentiated phenotype, as assessed by the high expression of CD27, CD28 and CD62L markers (central panel)." (PMID 25279468, 2014). "The involvement of CD28 in the modulation of protective immunity against T. cruzi was shown by mediating the activation of both CD4+ and CD8+ T cells, the production of IFN-γ, and, as a consequence, the production of NO efficient to control parasite growth during the acute phase of the infection." (PMID 25197170, 2014). "Furthermore, the absence of CD28 impairs development of memory CD4+ T cell responses resulting in failure to clear adult N. brasiliensis worms during secondary infection." (PMID 24516382, 2014). "The outcome and special contributions of MHC-I molecule H-2Db, the early anti-viral CD8+T cell response to a TMEV-infection, the reaction of CD4+ T helper and effector cells as well as regulatory T cells (Tregs) could not be differentiated in the present study, utilizing a generalized CD28-knockout." (PMID 37090733, 2023). "CD8 T cell activation was accompanied by depletion of CD8 T-cells with a resting (CD27+CD28+) phenotype without accumulation of partially (CD27−CD28−) or fully (CD27−CD28−) differentiated phenotypes indicating that differentiated effectors migrate to the site of infection." (PMID 22363665, 2012). "Following infection and washing, cells were cultured in the absence of TIQ-15 for 5 days, and then activated by CD3/CD28 stimulation." (PMID 39146384, 2024). "Both CTL populations were predominantly of the terminally differentiated effector memory (TEM2) phenotype, defined as CD28– CCR7– CTLs, and the frequencies of TEM2 CTLs did not change during SIVmac239 infection." (PMID 32922404, 2020). "Regardless of infection status, NK cells were uniformly CD38+ throughout most of infancy, expressed CD45RA and lacked expression of CD28 and CCR7 (data not shown)." (PMID 23293640, 2012). "The absence of CD28, CD40, CD40L, CD80/CD86 or 4-1BBL did either not affect viral replication in the early phase of infection or early viral titers were rather increased." (PMID 19621080, 2009). "After washing away free viruses at 2 hours post infection, cells were continuously incubated without activation for 5 days, and then activated at day 5 with CD3/CD28 stimulation to initiate viral replication." (PMID 19851458, 2009). "Furthermore, no clear CD4 or CD8 T cell activation, in relation to CD28 or CD127 expression, was observed post-infection." (PMID 37012228, 2023). "Next, we analyzed the cytokine production in the left popliteal lymph node that drains the site of infection for the high dose model using anti-CD3 and anti-CD28 antibodies, as a global stimulus, or BM-DCs loaded or not with SLA as a parasite-specific stimulus." (PMID 33673117, 2021). "However, the expression of CD28 mRNA in the spleen and tracheobronchial lymph nodes (TBLN) did not change in the BVDV-inoculated groups by five days post infection in vivo, regardless of a low (strain SD-1) or high (strain 1373) virulence ncp BVDV." (PMID 27617959, 2016). "HDACi (no cellular activation) pre-treatment reduced infection by 3-fold compared to resting CD4 T cells while PKCa-treated cells triggering intermediate or high activation levels had infection rates below or similar to resting CD4 T cells at 48 hpi, well below CD3/CD28-activated cells." (PMID 32196533, 2020).
immune diseases (20 papers, 2013 to 2025). "For example, we observed a complex pattern of colocalization between CD28 eQTL, nearby actQTLs, and immune disease GWAS variants." (PMID 35591976, 2022). "Lastly, we show that CD28-sensitive genes are enriched in GWAS regions associated with immune diseases, implicating a role for CD28 in disease development." (PMID 33223527, 2020). "Finally, we show that a proportion of variants associated with common immune diseases is enriched in CD28-sensitive genes, pointing towards the important role of this costimulatory pathway in disease pathogenesis." (PMID 33223527, 2020). "Among those, six gene knockouts resulted in an immune disease, including Cd28, Ndfip1, Skap2, Tmem258, Tnfrsf1a, and Tnfrsf9." (PMID 35591976, 2022). "The majority of the tested immune diseases showed more significant enrichment (permuted p-value < 0.01) for CD28-sensitive genes compared to TCR-sensitive genes." (PMID 33223527, 2020). "Taken together, our study provides new insights into the role of TCR and CD28 costimulation in the activation and proliferation of human naive and memory CD4 T cells, and the influence of these stimuli on immune disease susceptibility." (PMID 33223527, 2020). "Modulating T-cell activation by targeting the CD28 pathway with CTLA4-Ig has also been a successful approach in treating complex immune diseases." (PMID 33223527, 2020). "Agents targeting ICOSLG, IL6R, and CD28 are broadly applied in managing immune system diseases." (PMID 40868097, 2025). "We sought to investigate whether immune disease-associated loci were enriched for the genes, we identified as TCR or CD28-sensitive, thereby implicating the involvement of either of these stimulatory pathways in disease pathogenesis." (PMID 33223527, 2020). "Until 2006, the signalling properties of CD28 between rodent (mouse and rat) and human were considered rather similar and, for several years, in vivo mouse models have been used for study the function of CD28 costimulation in health and immune diseases." (PMID 29540686, 2018). "Targeting the T cell costimulatory molecules CD28 and OX40 is thought to be promising strategy for controlling T cell-mediated immune disorders." (PMID 27708417, 2016). "Recent studies suggested that CD28 could cooperate with CTLA-4 to mediate T-cell activation, and could be an effective target for applying to many immune diseases." (PMID 36676763, 2023). "Individually targeting CD28, CTLA-4 and PD-L1 might therefore represent a valuable therapeutic strategy to treat immune disorders where effector and regulatory T cell functions need to be differentially targeted." (PMID 24376655, 2013). "Thus, individually targeting CD28, CTLA-4 and PD-L1 with biological agents might represent a valuable therapeutic strategy to treat immune disorders where Teff and Treg functions need to be differentially targeted." (PMID 24376655, 2013). "The increased amount of CD4+CD28− T lymphocytes in patients with MHE indicates stronger immune dysfunctions than in patients without MHE, with persistent immune activation, increased production of TNFα, IFNγ and of molecules which may damage endothelial cells and tissues." (PMID 28751644, 2017). "However, significant differences were detected between IAC patients and non-IAC patients in the training cohort, including immune system disease, BDG positivity, gastrointestinal perforation, CD28+CD8+ T cell-count, DR+CD8+ T cell-count and CD38+CD8+ T cell-count (p< 0.05)." (PMID 39726780, 2024). "The role for CD28 on activated T cells is particularly pertinent as CD28 expression is lost on a proportion of activated T cells with age, in HIV infection, and in the number of immune disorders in primates (but not rodents), and the functional consequence of this loss of CD28 is unknown." (PMID 25347065, 2014).
hematological malignancies (9 papers, 2017 to 2025). "While CD8+CD28− regulatory T-cells in patients with hematologic disorders display a known immune-escape mechanism, we show that lenalidomide can overcome the immunosuppressive impact of CD8+CD28− T-cells." (PMID 29228683, 2017). "These G2 CARs have proven to be very effective, with Yescarta (a CD28 G2), Kymriah (a 4-1BB G2), BREYANZI (a 4-1BB G2), TECARTUS (a CD28 G2), and ABECMA (a 4-1BB G2) receiving regulatory approval for the treatment of several hematological malignancies." (PMID 35053463, 2022). "Unlike in many solid tumors, CD28 and CTLA-4 are innately expressed and play important biological roles in many hematological malignancies." (PMID 31195368, 2019).
infectious disease (8 papers, 2012 to 2023). A disorder directly resulting from the presence and activity of a microbial, viral, or parasitic agent in humans. "The role of CD28 on the enhancement of T cell-mediated immune responses suggests its potential for preventing infectious diseases." (PMID 28955336, 2017). "Therefore, post-transplant cyclophosphamide and CD28 costimulation blockade GvHD prophylaxis is able to induce recipient-specific tolerance while maintaining infectious disease immunity." (PMID 29127275, 2017). "Thus, the infectious disease, the CD28 T-helper signaling, and the calcium-induced T cell apoptosis pathways are the major pathways that characterize the CCI proteome samples relative to the sham samples." (PMID 22676642, 2012). "Only three genes overlap between the three studies, with CACNA1E being overexpressed, whereas CD28 and PCED1B had lower expression levels in patients with infectious disease." (PMID 37108169, 2023). "From the functional point of view, these soluble immune factors are related to CD28 co-stimulation, regulation of TLR by endogenous ligand, infectious disease, constitutive signaling by aberrant PI3K, adherens junction interactions, cellular response to stress, regulated necrosis, and pyroptosis." (PMID 36248816, 2022). "The major phenotypes identified in infectious diseases include CD28-negative CD39-positive CD8+ T cells in HIV infection, and the upregulation of the inhibitory receptor PD-1 on IL-10-secreting cells has also been observed in HIV, HBV and HCV." (PMID 36558866, 2022).
bacterial infection (6 papers, 2010 to 2024). "The association of the TLR with activated T cells, those having lost CD28 and expressing CD11b, suggests a role for TLR in the bacterial infection-induced T cell response." (PMID 21151520, 2010).
cardiovascular disease (6 papers, 2013 to 2024). "Expansions of cytotoxic CD4+ T cells characterized by loss of CD28 (“CD4+CD28− T cells” or “CD4+CD28null cells”) are closely associated with cardiovascular disease (CVD), in particular coronary artery damage." (PMID 28303136, 2017). "Several studies have linked cardiovascular disease with increasing senescent CD28- T cells." (PMID 32190092, 2020). "Moreover, these cells have been found within atheromatous plaque in animals and have been associated with vascular smooth muscle cell apoptosis and an increased risk of plaque rupture CD8+CD28- T cells were also found to be increased in patients with cardiovascular disease undergoing dialysis." (PMID 39456708, 2024). "Therefore, CMV has both direct and indirect roles (i.e., through the expansion of cytotoxic CD28- T cells) in promoting cardiovascular disease." (PMID 32190092, 2020). "These cells generally are thought to have a highly differentiated phenotype, lacking expression of the co-stimulatory molecule CD28, which has been associated with RA extra-articular manifestations and cardiovascular disease." (PMID 24267267, 2013). "Therefore, CD4+CD28 null cells correlated with CRP and serum albumin levels while important differences in items of CD4+CD28 null and CD8+CD28 null cells were found in patients with cardiovascular disease." (PMID 33816535, 2021).
inflammation (4 papers, 2016 to 2024). Aberrant reaction of the microcirculation characterized by movement of fluid and leukocytes from the blood into extravascular tissues. "To demonstrate the mechanism of CD28 deficiency in blast exposure-induced lung injury, we tested the hypothesis that blast exposure-induced lung inflammation, oxidative stress, and apoptosis are attenuated in CD28 knockout (CD28−/−) mice." (PMID 31565151, 2019).
kidney diseases (3 papers, 2017 to 2022). "In addition, immunosenescence seems to be more pronounced in patients with kidney diseases than in healthy controls, as shown by severe chronic inflammation, accumulation of immune cells with the senescent phenotype (CD28− T cells, CD14+CD16+ monocytes), and proinflammatory cytokine production." (PMID 36384564, 2022).
neurodegenerative disease (3 papers, 2025). A disorder of the central nervous system characterized by gradual and progressive loss of neural tissue and neurologic function. "Given that elevated systemic inflammation and decreased Tregs activity are common features of neurodegenerative diseases, further investigation into the interplay between Cd28+ Th cells and Tregs in ALS is warranted." (PMID 40072375, 2025).
hematological cancers (2 papers, 2021 to 2025). "Flow cytometric analyses of CD4+CD28− T cells confirmed the expected immunophenotype in BM from healthy donors and patients with different hematological cancers, suggesting a robust and efficient prospective isolation of this rare cell type." (PMID 34811546, 2021).
metabolic disorders (2 papers, 2018 to 2025). "Additionally, CD8+CD28−, CD8+PD1+, and CD8+CD28+PD1− T cell proportions in PBMC are closely associated with metabolic disorders, emphasizing their potential as biomarkers for immune and metabolic interactions in EC." (PMID 40136325, 2025).
bone disorder (1 paper, 2013). "Therefore, the contraction of the CD28-negative CD4+ T-cell pool that we observed in patients with bone disorders may have resulted from increased activation-induced apoptosis." (PMID 23448662, 2013).
colon polyps (1 paper, 2024). "Conversely, Eubacterium brachy may reduce the risk of colon polyps by decreasing the levels of CD4 on CD28+ CD4+ T cells." (PMID 39346904, 2024). "Additionally, Eubacterium brachy was a protective factor against colon polyps, with its mechanism of action being related to CD4 on CD28+ CD4+ T cells." (PMID 39346904, 2024).
connective tissue disorder (1 paper, 2022). A disease involving the connective tissue. "Altogether, the preclinical and clinical results support a role for both the ICOS and CD28 pathways in connective tissue disorders, and our data herein extend the findings to the specific fibrotic phenotype that characterizes SSc." (PMID 34986869, 2022).
movement disorder (1 paper, 2023). Neurological conditions resulting in abnormal voluntary or involuntary movement, which may impact the speed, fluency, quality and ease of movement. "The imbalance of CD28 and CTLA4 leads to high inflammatory tendency and dopamine neuron injury, which may contribute to the onset and exacerbation of movement disorders in MSA patients." (PMID 36831748, 2023).
CD28 also shares sentences with these, for which no sentence is quoted: Graves disease (6 papers); systemic sclerosis (6); schistosomiasis (4); chronic periodontitis (3); cutaneous T-Cell lymphomas (3); idiopathic pulmonary fibrosis (3); adenocarcinoma (2); adult T cell leukemia (2); Atherosclerotic lesion (2); benign ovarian tumor (2); Borrelia burgdorferi infection (2); brain tumors (2); cardiomyopathy (2); food allergy (2); gastric tumor (2); gram-negative bacterial infections (2); head and neck cancer (2); head and neck squamous cell carcinoma (2); heart failure (2); helminth infection (2); inflammatory skin disease (2); neurological disease (2); nosocomial infection (2); pituitary tumor (2); Primary Immunodeficiency (2); prostate (2); pulmonary hypertension (2); T-cell leukemia (2); Thrombocytopenia (2); vascular dementia (2).
A further 109 diseases each share a sentence with CD28 in 1 paper.